IL22 (interleukin 22)
Diseases named in the same sentence as IL22 in open-access papers (continued):
Sharing a sentence is not in itself a finding about the gene and the disease.
Insulin resistance (continued). "Blocking IL-22 signaling resulted in unfavourable effects on body weight, glucose tolerance and insulin sensitivity, whereas treatment with recombinant IL-22 proteins or IL-22 overexpression counteracted weight increase and improved hyperglycaemia, insulin resistance and inflammation." (PMID 28143481, 2017). "Interleukin-22 (IL-22) has beneficial effects on body weight, insulin resistance and inflammation in different mouse models, but its relevance for the development of type 2 diabetes in humans is unknown." (PMID 28143481, 2017). "Recombinant IL-22 (rIL-22) reduces the expression of genes related to lipogenesis and promotes the expression of genes with antiapoptotic, antioxidant and prosurvival activities, thus relieving hepatocyte injury and steatosis, ameliorating insulin resistance, and modulating metabolic syndrome." (PMID 34944732, 2021). "Although IL-22 was proven to exert protective responses in many pathological conditions, its extrahepatic complications might also contribute to mediating adipose tissue inflammation and insulin resistance in some circumstances." (PMID 34944732, 2021). "IL-22R1-deficient but not IL-22-deficient mice display higher weight gain and develop higher insulin resistance and glucose intolerance after HFD feeding compared with control mice, suggesting a redundant function of other IL-22R1 ligands, such as IL-20 and IL-24." (PMID 34944732, 2021). "In addition, the administration of exogenous IL-22 in genetically obese leptin-receptor-deficient (db/db) mice and mice fed with HFD reverses many of the metabolic symptoms, including hyperglycemia and insulin resistance." (PMID 26681840, 2015). "Liver-targeted IL-22 gene delivery via nanoparticles also alleviates HFD-induced hepatic steatosis, hyperglycemia, and insulin resistance." (PMID 40243151, 2025). "Improves glucose tolerance, reduces hyperglycemia, enhances IL-22 production, restores intestinal barrier integrity, promotes mitochondrial function via SIRT3, and reduces insulin resistance in HFD mice." (PMID 39963239, 2025). "We showed that IL-22 and REG3A have opposite effects on fat accumulation in the liver and insulin resistance development despite inducing a similar shift in fecal microbiota composition." (PMID 41027972, 2025). "We show thus that IL22 and REG3A have opposite effects on fat accumulation in the liver and insulin resistance development despite inducing a similar shift in fecal microbiota composition." (PMID 41027972, 2025). "We show that IL-22 and REG3A have opposite effects on fat accumulation in the liver and insulin resistance development despite inducing a similar shift in fecal microbiota composition." (PMID 41027972, 2025). "Increased IL-22 production by intestinal ILC3s also participates in improved polycystic ovary syndrome (PCOS) and relevant insulin resistance." (PMID 34944732, 2021). "In high sugar-induced insulin resistance and diabetes complications, AhR is crucial for maintaining ILC3, promoting the development and maturation of ILC3, and stimulating the secretion of IL-22 by ILC3 to inhibit inflammation levels, thereby preserving intestinal homeostasis." (PMID 39944639, 2025). "This suggests that granulosa cell knockdown of STAT3 does not affect the overall amelioration of insulin resistance by IL-22." (PMID 38734641, 2024). "Transplantation of fecal microbiota from women with PCOS or B. vulgatus-colonized recipient mice results in various negative effects on ovarian functions, insulin resistance, bile acid metabolism, interleukin-22 secretion, and fertility." (PMID 38362275, 2024). "Furthermore, they noticed that obese individuals with insulin resistance exhibited greater polarization and infiltration of CD4+ T cells that generated IL-22 in the subcutaneous adipose tissue." (PMID 37525285, 2023).
Insulin resistance (continued). "A recent study reported reduced levels of IL-22 in the serum and follicular fluid of PCOS patients, in addition to the fact that IL-22 administration could help to improve insulin resistance, ovarian dysfunction, and infertility in intestinal bacteria or a prenatal AMH-induced PCOS mice model." (PMID 36835989, 2023). "However, evidence shows that endogenous IL-22 and biologically active IL-22 do not influence the development of adiposity or metabolic alterations, nor do they influence body weight, insulin resistance, or glucose tolerance in mice." (PMID 34944732, 2021). "The action of IL-22 in regulating metabolic homeostasis was described, since treatment of db/db mice or mice fed a HFD with rIL-22 strongly reduces body weight, decreases blood glucose levels, and reverses various metabolic symptoms, including insulin resistance and hyperglycemia." (PMID 34944732, 2021). "In parallel, they observed no improvement in insulin resistance in HFD mice following a long-term and low-dose administration of recombinant mouse IL-22 (rmIL-22)." (PMID 37525285, 2023). "Thus, the decrease of IL-22 was not able to well reverse the PCOS phenotypes, leading to insulin resistance and ovary dysfunction." (PMID 33669557, 2021).
liver fibrosis (50 papers, 2014 to 2025). "In a group of patients with advanced liver fibrosis, liver steatosis was linked with lower serum concentrations of IL-4, IL-5, IL-9, IL-10, IL-13 and IL-22." (PMID 39200991, 2024). "For example, the number of liver-infiltrating IL-22+T cells increases in patients with HBV-associated liver fibrosis and is positively correlated with the liver fibrosis staging score." (PMID 37041599, 2023). "Contrastingly, several reports outlined a rather pathogenic function of IL-22 by promoting liver fibrosis and cirrhosis." (PMID 33851257, 2021). "Pathogenic roles of the IL-22 and IL-17-mediated type 3 immune response are identified in the development of liver fibrosis in MAPK-dependent manners by enhancing TGF-β signaling in hepatic stellate cells (HSCs)." (PMID 34944732, 2021). "Meanwhile, IL-22 was protective in chronic hepatitis C and schistosome infection, the high level of IL-22BP was associated with aggravation of hepatic fibrosis." (PMID 34211477, 2021). "IL-22 has a protective effect on liver cells, can protects against liver injury, hepatitis, and liver fibrosis caused by a variety of reasons, and can promote liver regeneration after partial hepatectomy." (PMID 32760208, 2020). "IL-22 ameliorates liver fibrosis by inhibiting hepatic stellate cells (HSC), and loss of miR-200a is associated with the development of liver fibrosis." (PMID 27819314, 2016). "Moreover, IL-22TG mice were protected from CCl4-induced liver fibrosis, as were mice pretreated with an adenovirus containing an IL-22 encoding gene." (PMID 33851257, 2021). "Similarly, IL-23 driven ILC3 production of IL-17A and IL-22 during hepatitis B virus (HBV) infection has been shown to be associated with liver fibrosis in human patients, with liver cirrhosis potentially driven by the recruitment of Th17 cells." (PMID 30893756, 2019). "Additionally, the development of liver fibrosis in our study was associated with significantly higher levels of IL-22 ant its receptors, suggesting a pro-fibrogenic role for the cytokine." (PMID 27681697, 2016). "In a study involving 74 CHB patients, 36 hepatitis B cirrhosis patients, and 10 healthy controls, IL-22 levels positively correlated with the degree of liver fibrosis." (PMID 39995661, 2025). "In an alcoholic mouse model of liver fibrosis, IL-22 ameliorated fibrosis partly by inhibiting hepatocyte autophagy and the PI3K/AKT/mTOR pathway." (PMID 39995661, 2025). "On the one hand, IL-22 attenuates liver fibrosis by activating the Nrf2-ARE pathway, reducing the level of oxidative stress and inhibiting the activation and proliferation of hepatic stellate cells (HSC)." (PMID 41562076, 2025). "In the BDL-induced mouse model of liver fibrosis, IL-22 was shown to increase collagen type I expression while significantly reducing α-SMA mRNA expression, suggesting its antifibrotic effect." (PMID 39995661, 2025). "In the context of liver fibrosis, IL-22 has been shown to ameliorate fibrogenesis by inducing senescence in hepatic stellate cells (HSCs), thereby reducing ECM production." (PMID 40607394, 2025). "In the schistosome-induced mouse liver fibrosis model, liposomal IL-22 improved fibrosis via the miR-let7a/STAT3 signaling pathway." (PMID 39995661, 2025). "The IL-10/IL-17A ratio observed in our study, as well as the ratio of IL-10/IL-22, varied between various degrees of hepatic fibrosis (F0-F3)." (PMID 40918132, 2025). "TH17 cells contribute to liver fibrosis by producing IL-17 and IL-22, which stimulate the production of TGF-β in the liver, enhance TGF-β signaling in HSCs, and promote collagen and pro-inflammatory cytokine production by HSCs and Kupffer cells." (PMID 39897543, 2025). "The plasma ratio of IL-10/IL-22 differentiates the degree of liver fibrosis (Kruskal-Wallis, p=0.03)." (PMID 40918132, 2025).
liver fibrosis (continued). "In a CCl4-induced mouse model of liver fibrosis, IL-22 attenuated fibrosis by regulating cell polarization, inhibiting the STAT3/Erk/Akt pathway, and increasing the M2/M1-KCs ratio of KCs." (PMID 39995661, 2025). "IL-22 has been found to have anti-liver fibrosis effects, IL-22 overexpression attenuates hepatic fibrosis by inhibiting the activation of HSCs and downregulating inflammatory cytokines." (PMID 39995661, 2025). "In a subgroup of patients with advanced liver fibrosis, SLD was linked with lower serum concentrations of IL-4, IL-5, IL-9, IL-10, IL-13 and IL-22 and higher concentrations of HGH and VEGF." (PMID 39200991, 2024). "Overexpression of IL-22 by gene targeting or delivery through adenovirus expressing IL-22 has previously been shown to reduce liver fibrosis and accelerate fibrosis resolution during recovery in the carbon tetrachloride (CCl4) model." (PMID 38811532, 2024). "In a mouse model, IL-22 has been demonstrated to cause HSC senescence, limit liver fibrosis, and hasten liver fibrosis resolution after recovery." (PMID 36826975, 2023). "By increasing CXCL9 and CXCL10 expression on hepatic stellate cells (HSCs), IL-22 also promotes inflammatory cell accumulation in the liver, leading to increased liver damage and hepatic fibrosis." (PMID 36839448, 2023). "The evidence for IL-22-mediated anti-fibrotic effects in the liver is quite strong; e.g., IL-22 was shown to contain liver fibrosis and promote its resolution in a mouse model of CCL4-induced liver injury and to induce HSC senescence." (PMID 35641678, 2022). "It has been revealed that in the progression of liver fibrosis, IL-17A functions together with IL-22 to enhance TGF-β in hepatic stellate cells." (PMID 35739565, 2022). "Exogenous administration of adenovirus-expressing IL-22 induces HSCs to enter senescent status, thereby alleviating alcohol-induced fibrosis in mouse liver and accelerating the resolution of liver fibrosis." (PMID 36611926, 2022). "Overexpression of IL-22 binding protein (IL-22BP), which is a competitive inhibitor of IL-22, can aggravate the progression of liver fibrosis and cirrhosis." (PMID 34434945, 2021). "We propose to trace the interaction of three molecules (IL-17A, IL-22, RA) and assess the possible impact of this trio on the development of liver fibrosis." (PMID 34211477, 2021). "In CCl4-induced liver fibrosis, IL-22 is capable to slow liver fibrosis progression via an increase in anti-inflammatory KCs to pro-inflammatory-KCs ratio." (PMID 34211477, 2021). "On the other hand, it has been reported that high levels of IL-22 positive cells and IL-22 in intrahepatic and peripheral blood are positively correlated with the progression of liver fibrosis and α- smooth muscle actin (α- SMA) level." (PMID 34434945, 2021). "IL-22RA1 knockout mice or mice with blockade of IL-22/IL-17 production by RAR-related orphan receptor gamma-t (RORγt) or aryl hydrocarbon receptor (AhR) antagonists exhibit reduced liver fibrosis." (PMID 34944732, 2021). "IL-22 can promote the proliferation of HSCs in vitro and accelerate the progression of liver fibrosis from hepatitis C virus recurrence after orthotopic liver transplantation (HCV-OLT)." (PMID 34434945, 2021). "In patients with hepatitis B cirrhosis, the infiltration of IL-22 positive cells in the liver is significantly higher than that in healthy individuals and is positively correlated with the stage of liver fibrosis." (PMID 33869241, 2021). "Overexpression of IL-22 reduces liver fibrosis by attenuating the activation of hepatic stellate cell (the main cell types involved in hepatic fibrosis), and down-regulating the levels of inflammatory cytokines." (PMID 32760208, 2020).
liver fibrosis (continued). "Blocking type 3 inflammation, either by IL-17+ cell depletion or by inhibition of IL17/IL22 production reduced the degree of liver fibrosis and prevented fibrosis progression in mouse fibrosis models of different etiologies." (PMID 33036244, 2020). "As a survival factor for hepatocytes, IL-22 plays a protective role in many kinds of liver diseases, such as hepatitis, liver fibrosis, or hepatocellular carcinoma (HCC) by binding to the receptors IL-22R1 and IL-10R2." (PMID 32760208, 2020). "For example, IL-22 has been associated with liver fibrosis severity in patients infected with HCV, with a possible pathological role residing in the accumulation of IL-22 in fibrotic areas due to its role in ameliorating liver tissue damage." (PMID 29892294, 2018). "IL-22 also prevents apoptosis of hepatic stellate cells and attenuates liver fibrosis in mice and rat models, and reported as a predictive severity marker in advanced stages of liver cirrhosis." (PMID 29892294, 2018). "Studies have shown that IL-17 exacerbates hepatic fibrosis in mice; however, co-expression of IL-17 and IL-22 has also been shown to ameliorate fibrosis." (PMID 28902848, 2017). "High IL-22 levels in cultures correlated with protection against hepatic fibrosis and portal hypertension." (PMID 28969688, 2017). "In contrast to it, an inverse correlation was noted among hepatic fibrosis extent and portal vein diameter with IL-22 produced by egg-stimulated and resting PBMCs clearly suggests a protective role of IL-22 against S. japonicum induced liver fibrosis." (PMID 28050571, 2016). "The study aimed to investigate the interplay between IL-22 and miR-200a in regulating liver fibrosis in vivo and in vitro." (PMID 27819314, 2016). "Our results reveal the interaction between IL-22 and miR-200a in regulating the development of hepatic fibrosis." (PMID 27819314, 2016). "On the other hand, others also demonstrated that IL-22 had a hepatoprotective role and alleviated the development of hepatic fibrosis." (PMID 27681697, 2016). "Collectively, these results suggested that miR-200a was involved in the regulatory function of IL-22 in alleviating liver fibrosis." (PMID 27819314, 2016). "A variety of studies reveal the relevance of IL-22 in liver fibrosis demonstrating its protective role." (PMID 26199463, 2015). "In the same murine model of hepatic fibrosis administration of IL-22 upregulated the expression of several antiapoptotic and antioxidant genes contributing to the attenuation of the oxidative stress." (PMID 26199463, 2015). "Another recent study demonstrated that IL-22-pathway-associated genes are significantly up-regulated in HBV-infected liver tissues, and IL-22+ cells in the liver positively correlate with liver fibrosis severity." (PMID 24927147, 2014). "The relationship between IL-22 and liver fibrosis remains controversial." (PMID 39995661, 2025). "Studies have reported that IL-22 is significantly upregulated in patients with liver fibrosis." (PMID 41562076, 2025). "Additionally, Interleukin-4 (IL-4), Interleukin-22 (IL-22) exerts both anti-inflammatory and pro-inflammatory roles in liver fibrosis." (PMID 39995661, 2025). "More recently, a short-acting IL-22-bispecific fusion protein that selectively targets the liver and pancreas alleviated hepatic steatosis and prevented the development of hepatic fibrosis in a 10-fold lower dose than the long-acting form of IL-22 administered in previous pre-clinical studies." (PMID 40794228, 2025). "The balance between anti-inflammatory and pro-inflammatory effects of IL-22 may determine its role in liver fibrosis, and its exact mechanisms require further investigation." (PMID 39995661, 2025). "Aside from the possible role in tissue repairing, IL-22 and IL-10 may also play an important role in the modulation of liver fibrosis, decreasing HSC activation and tissue inflammation." (PMID 37373379, 2023).